PIWIL1 (piwi like RNA-mediated gene silencing 1)
Diseases named in the same sentence as PIWIL1 in open-access papers (continued):
Sharing a sentence is not in itself a finding about the gene and the disease.
cancer (continued). "A lot of research has explored the action mechanisms of PIWIL1 on tumorigenesis and tumor progression in different cancers." (PMID 35003260, 2021). "The restricted expression of PIWIL1 in normal adult tissues, and its overexpression in a broad spectrum of malignancies, has led to the consideration of PIWIL1 as an ideal target for cancer diagnosis and treatment." (PMID 33718392, 2021). "Clinically, higher-level PIWIL1 is positively correlated with advanced clinical stage and worse overall survival of cancer patients." (PMID 35083142, 2021). "Unexpectedly we observed an accelerated fatty acid metabolism instead of anaerobic glycolysis in fueling HCC progression upon PIWIL1 overexpression Evidence of dysregulation of FAO as an energy source in cancer cells was limited." (PMID 33633112, 2021). "Given that the PIWIL1 is mostly expressed in the testis and broadly elevated in different cancers, PIWIL1 has the potential to be an ideal target for cancer diagnosis and therapy." (PMID 35003260, 2021). "Overexpression of PIWIL1 had been discovered to facilitate cancer progression and predict poor prognosis of patients with various cancers." (PMID 35003260, 2021). "We also discuss the most recent findings on the potential clinical applications of PIWIL1 in cancer diagnosis and treatment." (PMID 33718392, 2021). "In various cancer cells, high expressions of PIWIL1 and piRNAs lead to aberrant DNA methylation, tumor-suppressor genes silencing, and an abnormal “stem-like” state of cancer cells." (PMID 35003260, 2021). "This family contains four subtypes which any of them has a different role in cancer cells (PIWIL1 or HIWI, PIWIL2, PIWIL3, and PIWIL4)." (PMID 34193172, 2021). "RevMan 5.3 and STATA 12.0 statistical software programs were used to explore the relationships between PIWIL1 expression and the prognosis and clinicopathological features in cancer patients." (PMID 35003260, 2021). "Herein, we conducted this meta-analysis to identify the clinicopathological and prognostic value of the PIWIL1 expression in cancers." (PMID 35003260, 2021). "For now, this study is the most full-scale meta-analysis and systematic review which scientifically revealed the possible prognostic role of PIWIL1 expression level in cancers." (PMID 35003260, 2021). "The human genome encodes four PIWIL genes, known as PIWIL1 (HIWI), PIWIL2 (HILI), PIWIL3 (HIWI3), and PIWIL4 (HIWI2); some of which were found to be highly expressed in several human cancers." (PMID 32204558, 2020). "PIWIL1 staining was exclusively observed in the cytoplasm of cancer cells with a slight intensity (HScore: 1)." (PMID 33008024, 2020). "Because we found contradictory data in the literature, a multitumor panel of 16 malignant tumor types was analyzed in order to identify expression status of PIWIL1-2-3-4 genes in human cancers at RNA and protein levels." (PMID 33008024, 2020). "In this context, an aberrant expression of PIWIL1 and PIWIL2 have been associated with different types of cancer and showed a variable prognostic and diagnostic potential." (PMID 31443431, 2019). "Next, our further discoveries showed that PIWIL1 knockdown can recover the circadian rhythms to a certain extent in HeLa cancer cells, first indicating that PIWIL1 can play as a regulator for circadian clock." (PMID 31099187, 2019). "Several cancer-germline genes have been defined to stimulate PIWIL1 as a part of oncogenic pathways involved in cell proliferation." (PMID 31354629, 2019). "PIWIL1 participates in many physiological processes and current discoveries have shown that PIWIL1 is involved in tumorigenesis in various cancers." (PMID 31099187, 2019). "In this study, we aimed to assess an association between PIWIL1 and PIWIL2 expression and the prognosis of biliopancreatic cancer patients." (PMID 31443431, 2019).
cancer (continued). "Specifically, we identified 6 CpG sites (cg24838063, cg26677194, cg23887609, cg02382037, cg23548151, cg13900773) in the CpG island located in the promoter and first exon of PIWIL1, strongly demethylated in cancers." (PMID 31694219, 2019). "Previous studies reported that PIWIL1 plays an important role in cancer development, improving DNA methylation." (PMID 31354629, 2019). "The high expression rate of PIWIL1 in the cancer tissue was 54.2% (64/110), which was obviously higher than that in the corresponding adjacent tissue (40.9%, 45/110), with the difference being of statistical significance (χ2 = 4.053, P = 0.044)." (PMID 28634417, 2017). "The high expression rate of PIWIL1 in the cancer tissue was obviously higher than that in the corresponding adjacent tissue." (PMID 28634417, 2017). "There results indicate a reciprocal regulation between PIWIL1 and some cancer stem cells markers in CRC." (PMID 28634417, 2017). "Effects of Piwil1 on cancer cells viability, invasion and migration were evaluated by MTT, plate colony formation, transwell assay and nude mouse tumor xenograft assay." (PMID 26506848, 2015). "Global DNA hypomethylation and TE derepression, such as L1, is a common feature of cancer genomes in humans PIWIL1 and 2 overexpression has been observed in tumors from various tissues." (PMID 24932571, 2014). "Next, PIWIL1 mutation was less frequent in (a) lymphatic disseminated tumors of BRCA (p = 0.043) and COAD (p = 0.037) and (b) late stages in ESCA (p = 0.021) and READ (p = 0.019) carcinoma." (PMID 36672288, 2023). "Numerous studies have identified the overexpression of PIWIL1 gene/protein in various cancer types, suggesting that PIWIL1 might be involved in tumorigenesis or tumor progress." (PMID 35003260, 2021). "In sum, PIWIL1 has proven its tumor-promoting roles in various aspects of cancer biology." (PMID 33718392, 2021). "The potential use of PIWIL1 as a therapeutic target for human cancers has been studied previously." (PMID 33718392, 2021). "The PIWIL1 expression in CRC is positively correlated with the mRNA level of OCT4, a cancer stem cell marker, suggesting that PIWIL1 may contribute to the tumor stemless, which in turn strongly improves its metastatic potential." (PMID 35003260, 2021). "We observed that the PIWIL1-induced metabolic switch towards FAO in HCC might create an immunosuppressive microenvironment that facilitated cancer progression." (PMID 33633112, 2021). "In contrast to these oncogenic activities, previous studies suggested that PIWIL1 may have a tumor suppressor function in some cancer types, including chronic myeloid leukemia and acute myeloid leukemia." (PMID 33718392, 2021). "PIWIL1 could serve as a biomarker for prognosis and clinicopathological characteristics in various cancers." (PMID 35003260, 2021). "All studies detected the PIWIL1 expression levels in tissue samples, and based on the expression levels, which were mainly detected by immunohistochemistry (IHC), these cancer patients were categorized into high/positive and low/negative expression groups in the included studies." (PMID 35003260, 2021). "Whether PIWIL1 has a context-dependent function in different cancers, and whether PIWIL1 expression may serve as a biomarker for cancer subtyping and re-classification needs to be explored." (PMID 33718392, 2021). "Furthermore, the expression level of PIWIL1 has been found to be positively related to cell proliferation in several cancer cell lines." (PMID 35003260, 2021). "Besides, further larger-scale and high qualified multicenter studies including different tumor types are required to confirm the clinical value of PIWIL1 expression in cancers." (PMID 35003260, 2021). "This study also suggested that the pro-cancer stem cell activities of PIWIL1 might be mediated by the induction of two stem cell-related genes (CD44 and ALDH1)." (PMID 33718392, 2021).
cancer (continued). "Here, we review the most recent studies on PIWIL1, including its abnormal expression, cellular functions, mechanisms, along with its potentials as a biomarker for cancer diagnosis, prognosis evaluation, and a molecular target that enables the design of novel therapeutic strategies." (PMID 33718392, 2021). "Additionally, subgroup analyses, according to region, sample size, HRs extract method, and cancer type, suggested that the relationship between high PIWIL1 expression and poor OS was significant." (PMID 35003260, 2021). "In the present study, we found that PIWIL1 mediated E2-stimulated cancer cell proliferation." (PMID 32503542, 2020). "In most of malignant tumors belonging to this panel, we observed an expression profile comparable to IBCs associating variable PIWIL2 and PIWIL4 genes downregulation and an emerging aberrant expression of PIWIL1 and PIWIL3." (PMID 33008024, 2020). "Our observation indicated that PIWIL1 had a role in E2-stimulated cancer cells proliferation." (PMID 32503542, 2020). "To investigate the expression of PIWIL1 in human normal and cancerous tissues, we mined RNA-Seq data in The Cancer Genome Atlas (TCGA) and/or the Genotype-Tissue Expression (GTEx) databases, including 9736 tumoral (T) and 8587 non-tumoral (N) samples organized in 31 cohorts." (PMID 31694219, 2019). "Here we report that PIWIL1 can suppress circadian rhythms in cancer cells." (PMID 31099187, 2019). "However, PIWIL-1, a human homolog of the mouse MIWI protein, has been detected in the mitochondria of human cancer cells." (PMID 30153810, 2018). "PIWIL1 gene expression is elevated in many human cancer cells, and it has been suggested that PIWIL1 may be involved in tumorigenesis." (PMID 25007054, 2014). "Recent studies suggest that PIWIL1 maybe a marker for cancer cell proliferation as it is co-expressed with KI67, a reliable proliferating cell marker." (PMID 24932571, 2014). "Thus, the identification of aberrant PIWIL1 expression in tumor tissues might be useful in cancer diagnosis as well as in prognostic evaluation." (PMID 33718392, 2021). "Therefore, PIWIL1 is a promising biomarker of worse clinical outcomes in cancers." (PMID 35003260, 2021). "Firstly, PIWIL1 overexpression could be a common poor prognostic biomarker in cancers." (PMID 35003260, 2021). "However, the universal adaptability of PIWIL1 to predict prognosis for cancers is still unclear." (PMID 35003260, 2021). "PIWIL1 is a target for miR-154-5p, and this may explain the anti-cancer effects of miR-154-5p." (PMID 33109195, 2020). "Because of contradictory data in the recent literature regarding expression levels of PIWIL1-2-3–4 proteins in IBCs and other malignant tumors, a multitumor panel (n = 16) was analyzed to identify expression status of PIWIL1-2-3-4 genes at RNA level in most human cancers." (PMID 33008024, 2020). "PIWIL1, which is regulated by DNA hypomethylation, is over-expressed in lung tumor tissues, which might facilitate cancer cell proliferation, invasion, and migration and contribute to poor OS in patients with lung adenocarcinoma or malignant lung cancer phenotypes." (PMID 31399034, 2019). "PIWIL1 is extensively expressed in human tissues, including prostate, ovary, brain, liver, heart, kidney, and skeletal muscle, and it plays a crucial role in the self-renewal of human stem cells and RNA interference; in addition, it affects the proliferation of cancer cells." (PMID 28634417, 2017). "This study proposed a putative axis of piR-823/PIWIL1/DNMT3B/CDH1 that appears to be involved in EMT and cancer stemness in OC, providing a basis for future mechanistic studies." (PMID 41596471, 2026). "Among the four PIWI proteins expressed in humans, PIWIL1 and PIWIL2 seem to be the most promising candidates to be prognostic biomarkers in cancer." (PMID 38303021, 2024).
cancer (continued). "There are four known human PIWI homologs: PIWIL1 (HIWI), PIWIL2 (HILI), PIWIL4 (HIWI2), and PIWIL3 (HIWI3), all of which have been shown to be expressed in a number of different cancer tissues." (PMID 39596284, 2024). "Studies have also shown that PIWIL1 induces hypermethylation of PTEN by increasing the expression of DNMT1 and inhibiting the tumor suppressor PTEN to promote cancer progression." (PMID 38031146, 2023). "In previous studies, PIWIL1, PIWIL2, and PIWIL4 have been reported to function in cancer cell proliferation, metastasis, and invasion." (PMID 38033031, 2023). "We have shown in published work that RASSF1C promotes cancer stem cell development, migration, and drug resistance, in part, by promoting EMT through a mechanism that involves up-regulation of the PIWIL1-piRNA axis." (PMID 36826019, 2023). "Other molecules, such as FOXA1, SETD2, Hes5, C/EBP-δ, PRMT5, METTL3, Piwil1, PLK1, ERK1/2, and a series of miRNA, indirectly modulate the sensitivity of cancer cells to drugs by regulating FBXW7." (PMID 36998461, 2023). "In addition, in a significant fraction of CRC, the PIWIL1 gene was ectopically activated accompanied by demethylation of gene promoter, together with production of germline factors required for piRNA, which is a promising application of cancer-specific immunotherapies." (PMID 35637965, 2022). "Upregulation of PIWIL1 drastically induces tumor cell proliferation, epithelial-mesenchymal transition (EMT), invasion, cancer stem-like properties, tumorigenesis, metastasis and chemoresistance, probably via piRNA-independent mechanisms." (PMID 33718392, 2021). "The core CT genes include CMTM1, CT83 (CXorf61), EZHIP (CXorf67), DCAF4L2, KHDRBS3, LEMD1, PIWIL1, and SPATA6, which contribute to cancer progression and metastasis." (PMID 33426787, 2021). "In cancer, overexpression of PIWI proteins PIWIL1 and PIWIL2 has been observed in several types of carcinoma, including breast, esophageal, gastric, ovarian and colorectal cancers." (PMID 33672595, 2021). "The four human PIWI proteins PIWIL1, PIWIL2, PIWIL3 and PIWIL4 can be included in the cancer/testis antigens (CTAs) class and their deregulation is involved in cancer cell proliferation, apoptosis and stemness, genomic integrity, invasion and metastasis." (PMID 33008024, 2020). "Some of these pathway genes (PIWIL1, PIWIL2, TDRD1 and MAEL) are categorized as cancer/testis genes due to their restricted expression in testis but in recent years, have been observed to be aberrantly expressed in multiple cancers." (PMID 33374923, 2020). "Our comprehensive analysis revealed a more differentiated pattern where PIWIL1, MAEL and HENMT1 had increased expression, while PIWIL2, PIWIL4 and TDRD1 had decreased expression when comparing benign and malignant tumor samples." (PMID 33374923, 2020). "Interestingly, PIWIL1 has been listed among very highly expressed cancer testis genes (EECTGs), considered epigenetic drivers of cancer as when expressed, they confer a selective growth advantage to the transformed cell; they therefore may represent potential targets for new cancer therapies." (PMID 31694219, 2019). "First, we screened cancer cell lines for PIWIL1 expression, and the results showed that PIWIL1 was expressed in HeLa, MCF7, HepG2, A549 and HT‐29 cancer cells." (PMID 31099187, 2019). "Despite this experimental evidence elucidating the role of PIWIL1 and MAEL in cancer is difficult as differing effects are observed." (PMID 24932571, 2014). "According to The Human Protein Atlas, a commercially available antibody reliably stained testicular tissue, whereas it did not detect PIWIL1 in most of the cancer tissues." (PMID 38303021, 2024). "Knockout of PIWIL1 in CaSki cells, achieved via CRISPR-Cas9, led to a significant reduction in cell viability, increased apoptosis, and decreased proliferation, confirming PIWIL1’s role in promoting cancer cell growth and stemness." (PMID 39596284, 2024).
cancer (continued). "In addition, PIWIL1-induced metabolic transformation to FAO creates an immunosuppressive microenvironment, promoting cancer progression." (PMID 38031146, 2023). "Moreover, a study about PIWIL2 demonstrated that PIWIL2, as well as PIWIL1, can be a biomarker for CRC because of its higher expression in this kind of cancer." (PMID 34193172, 2021). "Based on a meta-analysis of TCGA and GTEx data, we found that PIWIL1 presents unique features among PIWILs, as PIWIL2 and PIWIL4 are frequently deregulated in cancers but are also expressed in several normal tissues, while PIWIL1 is almost absent in non-transformed tissues." (PMID 31694219, 2019). "PIWIL1, PIWIL3, and PIWIL4 act as intrinsic regulators of the self-renewal capacity of germ line and hematopoietic stem cells, and are believed to be involved in cancer development." (PMID 28422722, 2017). "Because the anti-cancer agent, betulinic acid (BA), has been shown to down-regulate PIWIL1 gene expression, we studied the effects of BA and RASSF1C/IGFBP-5 interaction on PIWIL1 gene expression and β-catenin protein levels." (PMID 25007054, 2014). "Thus, we wanted to determine if RASSF1C mediates its effects on cancer cells through interactions with IGFBP-5 and PIWIL1." (PMID 25007054, 2014). "Since small molecules that bind directly to PIWIL1 and alter its function have not yet been achieved, targeting the signaling pathways that contribute to PIWIL1 dysregulation has been exploited as new approaches to treat PIWIL1-expressing cancers." (PMID 33718392, 2021). "Moreover, also HIWI or PIWIL1, PIWIL2, and PIWIL4 (members of PIWI subfamily) have been proven to play important roles in cell proliferation and apoptosis in several types of cancers." (PMID 34193172, 2021). "Moreover, the expression of PIWIL1 in CRC has been positively correlated with the mRNA level of OCT4, a cancer stem cell marker, indicating that this gene may contribute to the tumor stemless, which in turn is strongly related to its metastatic potential." (PMID 31694219, 2019). "Furthermore, PIWIL1 and PIWIL2 are significantly elevated in invasive ductal carcinoma (IDC), which promotes cancer development by aberrant DNA methylation resulting in genomic silencing and inducing a stem-like state of cancer cells." (PMID 31399034, 2019). "Finally, the human PIWIL1 protein (MIWI in mouse) was detected in the mitochondria of human cancer cells but not in mouse mitochondria." (PMID 30153810, 2018). "In addition, human PIWIL1’s role in some cancers is reported to be independent of gene silencing." (PMID 37733654, 2023). "In addition, research indicated that PIWIL1 and PIWIL2 expression were significantly increased in invasive ductal carcinomas (IDCs), inducing a stem-like state of cancer cells through abnormal DNA methylation, generating genomic silencing and ultimately promoting cancer development." (PMID 35637965, 2022). "However, the difference in expression level for PIWIL1 versus PIWIL2 and PIWIL4 contributing to better patient outcome was expected given the difference we observed when comparing their expression in benign and malignant tumors as well as low grade OC versus high grade OC." (PMID 33374923, 2020). "MIR205HG, PIWIL1, and SLC16A9 are the only genes that were upregulated in cancer samples across all racial groups, but they do not impact survival." (PMID 40558258, 2025).